STAT3 (signal transducer and activator of transcription 3)
Diseases named in the same sentence as STAT3 in open-access papers (continued):
Sharing a sentence is not in itself a finding about the gene and the disease.
squamous cell carcinoma (continued). "Furthermore, work with STAT3-targeted shRNA demonstrated enhanced radiosensitivity in the human squamous cell carcinoma cell line A431, and Stattic impaired increased radiosensitivity in orthotopic xenograft UM-SCC-17B tumors." (PMID 23382914, 2013). "The first involvement of STAT3 in the regulation of Bcl-xL has been proved by Grandis and colleagues throughout the identification of a correlation between the constitutive activation of STAT3 and a higher expression of Bcl-xL in squamous cell carcinomas of the head and neck." (PMID 33803452, 2021). "Recent studies have also found that, in squamous cell carcinoma (SCC), circFAT1 can prevent Src homology 2 domain-containing protein tyrosine phosphatase 1 (SHP-1) from dephosphorylating STAT3 and promotes STAT3 activation by binding to STAT3 in the cytoplasm." (PMID 38172648, 2024). "We previously showed the potential for STAT3 decoy-loaded microbubbles, in conjunction with ultrasound targeted microbubble cavitation (UTMC), to decrease tumor growth in murine squamous cell carcinoma." (PMID 33206698, 2020). "Ezrin, ERK, STAT3, and AKT appear to be involved in the progress from carcinoma in situ in the tongue into squamous cell carcinoma." (PMID 32281236, 2020). "Overexpression of STAT3 has been reported to potentiate growth, survival, and chemo- and radio-resistance of NSCLC and human squamous cell carcinoma cells." (PMID 31847229, 2019). "Both EMSA and ChIP assays confirmed that STAT3 and EGFR bind to and regulate the gene promoter for iNOS in epidermoid carcinoma cells." (PMID 24743777, 2014). "EGFR has been shown to initiate multistage skin carcinogenesis in murine models through activation of STAT3 and ErbB2 and EGFR family receptors have been demonstrated to be frequently amplified in squamous cell carcinoma of uterine cervix." (PMID 20977777, 2010). "Moreover, luteolin reduces Src/STAT3/S100A7 which inhibits the invasion and migration of squamous carcinoma." (PMID 39830909, 2025). "In contrast to squamous carcinoma, neither STAT3 nor JAK1 presented any observable differences in adenocarcinoma tissues." (PMID 39099000, 2024). "In addition, the migration of squamous carcinoma cells has been found to be modulated by luteolin-induced reduction in expressions and activities of S100A7, Src, and STAT3." (PMID 32224968, 2020). "Similarly, an in vivo model of squamous cell carcinoma driven by constitutive activation of Src showed increased levels of activated PDK1, STAT3, and ERK1/2 in the lesioned tissue." (PMID 30622697, 2019). "It was found that p-STAT3 could be detected in 6 of 38 (15.8%) non-cancerous cervical epithelia, in 84.0% (21/25; p<0.01) adenocarcinomas and in 36 of 43 (83.7%; p<0.01) squamous cell carcinomas." (PMID 25061499, 2014). "The expression rates of intrinsic STAT3 inhibitor PIAS3 were 52.6% (20/38) among noncancerous epithelial tissues but reduced to 16.0% (4/25; p<0.01) and 11.6% (5/43; p<0.01) in cervical adenocarcinoma and squamous carcinoma samples, respectively." (PMID 25061499, 2014).
brain tumor (81 papers, 2008 to 2026). "Upon activation, STAT3 is phosphorylated and persistent phosphorylation is linked with brain tumor grade; with GBM showing the highest levels of STAT3 phosphorylation." (PMID 33178210, 2020). "While MT330 cells expressing an empty vector (EV MT330) formed brain tumors, loss of STAT3 markedly inhibited tumor formation." (PMID 29774125, 2018). "Tumor-associated astrocytes in primary brain tumors were also recently found to express STAT3 and PD-L1 at high levels and to confer an immunosuppressive environment through increased production of cytokines such as interleukin (IL)–10 and transforming growth factor– β (TGF-β)." (PMID 32399646, 2020). "Studies targeting OSMRβ and STAT3 suggest that a clinical therapeutic that disrupts OSM/OSMRβ/STAT3 signaling can repress brain tumor growth and increase chemoresistance in aggressive brain tumors." (PMID 37841259, 2023). "A study in brain tumor cells suggested that downregulation of TET1 led to a significant reduction of STAT3 in transcript level." (PMID 36658614, 2023). "For example, EVs loaded with curcumin or a signal transducer and activator of transcription 3 (Stat3) inhibitor induce microglial apoptosis and suppress brain tumor growth." (PMID 37596642, 2023). "LncRNA CYB561D2 has been indicated to activate STAT3 and lead to the immunosuppression in brain tumor." (PMID 36289463, 2022). "EGFRvIII and OSMR are obligate co-receptors in maintaining oncogenic STAT3 signaling in mouse astrocytes and human brain tumor stem cells." (PMID 35954323, 2022). "The STAT3 signaling pathway influences recurrence and the malignancy of glioma tumors and is extensively activated by phosphorylation in brain tumors." (PMID 35328780, 2022). "This study also found that intranasal administration of GNVs that encapsulated with the Stat3 inhibitor JSI-124 significantly inhibited Stat3 activation in a mouse model of brain tumours planted with GL26 cells." (PMID 36588940, 2022). "The use of PPAR gamma agonists in GBM cells is known to reduce brain tumor stemness, cell proliferation, and invasive capacity and, also, by reducing STAT3 activation." (PMID 33182324, 2020). "Histopathological analysis of brain tumors demonstrated STAT3 to be overexpressed in patients with grade III astrocytomas and grade IV GBMs; increased STAT3 levels are negatively associated with MS in these patients." (PMID 33173024, 2020). "This suggests that STAT3 phosphorylation is the critical role in driving lncRNAs regulation similar to miR155HG in malignant brain tumor." (PMID 30898167, 2019). "In brain tumors, STAT3 was shown to play a critical role in mesenchymal transition associated with angiogenesis, extensive necrosis and enhanced inflammatory response." (PMID 29423098, 2018). "Histology analysis of xenograft brain tumors revealed that the pathologies of GBM-R2I2/sh-STAT3 tumors after 5 Gy RT exhibited dramatically reduced tumor size in 3T MRI compared with those of GBM-R2I2/sh-Scr tumors post-RT (5 Gy)." (PMID 30551687, 2018). "In particular, STAT3 is activated during the apoptotic involution of mammary gland and the suppression of brain tumours." (PMID 27769057, 2016). "Another interesting function of CEBPB is its role in the occurrence of mesenchymal phenotype in brain tumors where it is a synergistic initiator of mesenchymal transformation with STAT3." (PMID 24597747, 2014). "This is especially relevant in brain tumors, where STAT3 is important in the mesenchymal transformation." (PMID 23094050, 2012). "STAT3 is a known oncogene recently identified as a driver of mesenchymal transformation in brain tumors, while SS18L1 is a protein normally required for calcium-dependent dendritic growth and branching in cortical neurons." (PMID 21980275, 2011). "We measured the percentage of PBMCs displaying p-STAT-3 in 19 healthy donors and 45 patients with primary brain tumors." (PMID 19900287, 2009).
brain tumor (continued). "Additionally, there was a significant positive correlation between expression of IGF2 and NFκB, GATA2 and STAT3 in brain tumor patients sampled in the CGGA dataset." (PMID 38853689, 2024). "STAT3 inhibitors are in clinical trials for pediatric patients with brain tumors (NCT04334863)." (PMID 37509316, 2023). "Our study also focused on the role of p-STAT3 in the immunobiology of brain tumors." (PMID 35316217, 2022). "To understand the origins of chemoresistance involving IL-6/STAT3 signaling, we used in vitro co-culture systems to investigate the contribution of microglia as a brain tumor microenvironment cellular source of paracrine cytokines that promotes acquired drug resistance in Group 3 MB." (PMID 35159191, 2022). "Indeed, STAT3 inhibition has already been proposed as a therapeutic strategy for brain tumours, despite its role in autophagy induction; here, we propose that combined inhibition of both autophagy and STAT3 impairs MB growth." (PMID 34302498, 2021). "Moreover, the oral administration of pimozide suppressed the growth of brain tumors by inhibiting STAT3 and inducing autophagy-mediated apoptosis." (PMID 32971907, 2020). "Upregulated STAT3 found in reactive astrocytes promotes the metastasis of brain tumors in patients." (PMID 32759670, 2020). "MB brain tumor-initiating cells expressing CD133 drive recurrence mediated by STAT3 activation." (PMID 31297057, 2019). "In conclusion, we provide first proof-of-concept evidence that intratumoral targeting of oncogenes like Stat3 using lipopolyplexsosomal siRNA for the treatment of brain tumors is feasible and leads to improved overall survival in a murine, syngeneic, orthotopic transplantation model." (PMID 30857197, 2019). "These efforts may lead to the development of new and highly specific treatments selectively targeting the expression of oncogenes such as STAT3, an avenue recently opened in a clinical trial focusing on another gene target in brain tumors (NCT03020017)." (PMID 30857197, 2019). "Therefore, ARP-dependent inhibition of Src/STAT3 pathway seems to support the potential of ARP for brain tumor treatment." (PMID 29464048, 2018). "STAT3 mediated downregulation of pro-inflammatory cytokines, and chemokines production is one of the contributing factors to the suppression of immunological response in brain tumors." (PMID 28346397, 2017). "Some groups have reported a correlation between brain tumor grade and STAT3 activation levels." (PMID 28346397, 2017). "Finally, since overexpression of CB1 correlated with STAT3 activity in almost all brain tumor tissues and GBM primary cell lines analyzed, we determined if inactivation of CB1 by siRNA knockdown reversed this finding." (PMID 26008966, 2015). "Similarly, for the brain tumor case study, NGF identified a key logic function which associates the mesenchymal phenotype with the upregulation of STAT3 and downregulation of SS18L1." (PMID 21980275, 2011). "STAT3 inhibition represents a novel target in the treatment of brain tumors." (PMID 20840775, 2010). "In the context of the treatment of brain tumors, it was hypothesized that GFDNs may deliver the anti-signal transducer and activator of transcription 3 (Stat3) inhibitor JSI-124 to the brain via the i.n. route and subsequently inhibit the implanted GL26 tumor growth." (PMID 33336066, 2020). "Stat3 upregulates the expression of lysosomal proteases cathepsin‐B and cathepsin‐L under physiological conditions and, thus, may facilitate cathepsin‐B enhanced tissue invasion and lysosomal‐mediated cell death regulation in brain tumors." (PMID 29949238, 2018).
brain tumor (continued). "Interestingly, further analysis revealed that the xenograft tumor we tested in vivo (X1016) also has amplification of EGFR (unpublished data from G.Y.G, UAB Brain Tumor Core Facility) in addition to high levels of activated STAT3 and NF-κB, suggesting a probable classical genetic subtype." (PMID 24244348, 2013). "Analysis of brain tumors detected STAT3 overexpression in more than half of the patients with grade IV GBM cells, validating STAT3 as an important clinical target in GBM therapy." (PMID 40396025, 2022). "Cucurbitacin-I and WP1066 administration or shRNA knockdown resulted in on-target JAK2/STAT3 inhibition and dramatically reduced GBM-derived Brain tumor stem cells." (PMID 29423098, 2018). "P-STAT3 was clearly detectable in brain tumor xenografts from vehicle-treated mice, whereas WP1066 treatment clearly reduced the level of p-STAT3, indicative of the inhibition of STAT3 activity." (PMID 26518290, 2015). "Because of its ability to reduce p-STAT3 levels in the NSC11 orthotopic xenografts, the effect of WP1066 on the radioresponse of these brain tumors was determined." (PMID 26518290, 2015). "To test the direct involvement of STAT3 pathway activation in the NF-κB pathway downstream of CHI3L1 action, we used WP1066, a selective inhibitor of STAT3 phosphorylation currently used in clinical trials for pediatric and adult brain tumors." (PMID 41480772, 2026). "For example, it has been suggested that ABCG2, FECH, and HO‐1 could serve as indicators of treatment outcome for ALA-PDT of brain tumors, while in HNC, STAT3 could be used as a molecular marker of cumulative photoreaction therapy monitoring." (PMID 34302323, 2021). "p-STAT3-oriented immunohistochemistry was performed on tissue microarrays constructed with the brain tumors and surrounding tissues of the animals with and without resveratrol treatment." (PMID 30176837, 2018). "Evidence from other tumor models suggests that metformin inhibits STAT3, but there is no specific data on brain tumor initiating cells (BTICs)." (PMID 28030813, 2017). "Additionally, pacritinib could be used as a salvage therapy for patients with a TMZ-resistant recurrent disease, as STAT3 inhibition sensitizes TMZ-resistant, patient-derived brain-tumor-initiating cell (BTIC) cultures." (PMID 31269723, 2019). "For instance, OPB-31121, which specifically inhibits STAT3-phosphorylation was recently investigated in patients with advanced solid tumors (but not brain tumors) in a phase I trial and showed the potential to stabilize (n = 8) or reduce (n = 2) tumors (n = 18)." (PMID 28030813, 2017). "In contrast to AKT1, STAT3 phosphorylation was not significantly changed after stimulation of LN18 cells with S1P despite a previously reported down-regulation of phosphorylated STAT3 in brain tumor stem cells after stimulation with the S1P analogue fingolimod." (PMID 26887055, 2016).
T-LGL leukemia (81 papers, 2013 to 2025). "For instance, LGL leukemia patients frequently present a mutation of the signal transducer and activator of transcription 3 (STAT3) gene." (PMID 41141147, 2025). "In both RA and LGL leukemia, somatic mutations can occur in genes involved in hematopoiesis, including STAT3, TET2, and DNMT3A, suggesting their overlapping etiologies and highlighting the role of inflammation-driven leukemogenesis." (PMID 41141147, 2025). "In LGL leukemia, STAT3 mutations are correlated to specific disease phenotypes and response to treatment." (PMID 39497832, 2024). "In some forms of cancer, such as large granular lymphocytic T cell leukemia, mutations occurring in STAT3 itself lead to increased magnitude or duration of STAT3 phosphorylation." (PMID 38611065, 2024). "Although both Felty Syndrome and LGL leukemia patients with concomitant RA have been reported to display STAT3 mutations, this is the first time that STAT3 mutations have been reported in a cohort of standard RA patients." (PMID 39497832, 2024). "CD8+ cell DNA was isolated and analyzed via droplet digital (dd)PCR to detect STAT3 mutations common in LGL leukemia: Y640F, D661Y, and the S614 to G618 region." (PMID 39497832, 2024). "Of note, LGL leukemia patients with multiple STAT3 mutations are more likely to experience concomitant RA." (PMID 39497832, 2024). "Somatic gain-of-function STAT3 mutations are demonstrated in 28–75% of T-LGL leukemia and 30–48% of NK-LGL leukemia." (PMID 38611065, 2024). "LGL leukemia is associated with specific immunophenotypic and molecular features, particularly STAT3 and STAT5 mutations and activation of the JAK-STAT3, Fas/Fas-L and NF-κB signaling pathways." (PMID 38610985, 2024). "Perhaps these increased rates of RF and anti-CCP in LGL leukemia can be explained by the presence of increased JAK/STAT signaling or activating STAT3 mutations as observed in our cohort." (PMID 39497832, 2024). "Felty Syndrome, a subtype of RA characterized by symptoms similar to LGL leukemia such as concomitant neutropenia and splenomegaly, demonstrates a STAT3 mutation rate of 43%." (PMID 39497832, 2024). "Perhaps the persistence of autoreactive T lymphocytes, probably in combination with other factors, leads to increased risk for the occurrence of activating point mutations of the STAT3 gene, which is considered a hallmark of T-LGL leukemia." (PMID 36362126, 2022). "Several activating mutations in the SH2 domain of STAT3, such as D661V and D661Y, have been identified in T-cell large granular lymphocytic leukemia (T-LGL) patients." (PMID 35752777, 2022). "In diagnostically unclear cases of neutropenia and/or splenomegaly in patients with ARDs, the detection of STAT3 mutations by NGS can indicate the diagnosis of T-LGL leukemia." (PMID 36117975, 2022). "We report a patient diagnosed with T-cell LGL leukemia with a rare γ/δ type and STAT3 mutation (Y640F)." (PMID 35600388, 2022). "Constitutive activation of the signal transducer and activator of transcription 3 (STAT3) signaling pathway is a molecular hallmark of T-LGL leukemia." (PMID 36117975, 2022). "STAT3 mutations are generally found almost exclusively in CD8+ rather than CD4+ patients, and more specifically, CD8+ CD16+ CD56- T-LGL leukemia patients exhibit more STAT3 mutations." (PMID 35646651, 2022). "Numerous studies have associated STAT3 mutations with moderate and severe neutropenia in LGL leukemia." (PMID 35646651, 2022). "STAT3 has long been known for its fundamental pathogenic role in T-LGL leukemia because it acts on the expression of many genes related to cell survival." (PMID 34873301, 2022). "The STAT3 mutation is found in 30% of NK-LGL leukemia as well as in 30-40% of T-LGL leukemia, linking the two entities." (PMID 35178350, 2022). "This STAT3 mutation prevalence in the LGL leukemia/RA group is similar to the frequency in previously published studies in LGL leukemia." (PMID 35646651, 2022).